INS (insulin)
Diseases named in the same sentence as INS in open-access papers (continued):
Sharing a sentence is not in itself a finding about the gene and the disease.
type 2 diabetes (continued). "For many patients, this trajectory leads to the need for insulin therapy—approximately one in three individuals with type 2 diabetes will require insulin therapy within seven years of diagnosis." (PMID 40937414, 2025). "Pancreatic β-cells belong to the endocrine part of the pancreas, which is responsible for the secretion of insulin to maintain the body’s blood glucose levels and is closely related to the occurrence of type 2 diabetes." (PMID 40077469, 2025). "Insulin signaling is a well-known factor in the development of Parkinson’s disease in patients with type 2 diabetes." (PMID 40332751, 2025). "Human studies also support these effects: higher intake is linked to lower glucose, insulin, and HOMA-IR, and serum spermidine inversely correlates with type 2 diabetes risk." (PMID 41300451, 2025). "Multiple studies have focused on elucidating the relationship between miRNAs and glucose metabolism; for instance, miR-122, miR-126, and miR-20b-5p affect insulin function and are elevated in patients with type 2 diabetes." (PMID 41009376, 2025). "Type II diabetes mellitus (T2DM) is a metabolic disorder that is characterized by chronic hyperglycemia, which is caused by insulin resistance along with defective insulin secretion." (PMID 40943086, 2025). "Summary of randomized controlled trials investigating once-weekly insulin in type 1 and type 2 diabetes." (PMID 40937414, 2025). "By elucidating these pathways, we propose new therapeutic avenues targeting GSV trafficking to improve insulin sensitivity and combat type 2 diabetes." (PMID 40806697, 2025). "Dietary fiber plays a significant role in glycemic control and improving insulin sensitivity among individuals with type 2 diabetes." (PMID 40808850, 2025). "Among the patients with type 2 diabetes (n = 34), 21 (61.8%) were treated with metformin, 8 (23.5%) with insulin, 6 (17.6%) with DPP-4 inhibitors, and 2 (5.9%) with sulfonylureas." (PMID 40564192, 2025). "In inflammatory conditions such as type 2 diabetes, insulin can increase endothelin-1 (ET-1) leading to vasoconstriction via the mitogen-activated protein kinase (MAPK) pathway." (PMID 40281528, 2025). "The pathogenesis of type 2 diabetes (T2D) is complex and involves intricate signaling pathways in insulin secretion and action." (PMID 40568093, 2025). "The pancreas regulates glucose homeostasis through the rhythmic secretion of insulin and glucagon into the portal circulation-an essential process that is disrupted early in the pathogenesis of type 2 diabetes." (PMID 42281561, 2025). "It is also associated with weight gain; the average weight gain after 10 years of insulin therapy is ≈7 kg in patients with type 2 diabetes." (PMID 40036884, 2025). "Type 2 diabetes (T2D) and obesity are chronic metabolic diseases marked by impaired insulin signaling, systemic inflammation, and metabolic reprogramming." (PMID 41514860, 2025). "This suggests the potential role of IGF-1 as a novel therapeutic target, also in combination with insulin, in therapeutic strategies to repair impaired glucose metabolism in the treatment of dementia in sporadic Alzheimer’s disease and type 2 diabetes." (PMID 40283962, 2025). "In animal models, FMT from healthy donors has been shown to improve insulin sensitivity and reduce adiposity, suggesting a role in managing metabolic syndrome and type 2 diabetes." (PMID 40901203, 2025). "Type 2 diabetes (T2D) is characterized by hyperglycemia due to impaired insulin utilization, and current therapies face notable limitations." (PMID 41252252, 2025). "Type 2 diabetes mellitus (T2DM) is a long-term metabolic disease marked by impaired insulin sensitivity and dysfunction of pancreatic β-cells." (PMID 40740642, 2025). "The proposed approach is applied to simulate the insulin-glucose regulatory system under different pathological conditions, including type 1 diabetes, type 2 diabetes, hyperinsulinemia, and hypoglycemia." (PMID 41345203, 2025).
type 2 diabetes (continued). "This study examined the relationship among inflammatory markers, mtDNA DAMPs, and insulin sensitivity/resistance, and evaluated their response to three dietary interventions in type 2 diabetes." (PMID 41156500, 2025). "Extensive evidence supports the clinical advantages of CGM across different insulin therapies, including in individuals with type 2 diabetes." (PMID 41268167, 2025). "It plays a crucial part in the development of atherosclerosis, type-2 diabetes mellitus, and metabolic syndrome (MS) since it is involved in the production, storage, and release of insulin." (PMID 39817379, 2025). "In individuals with type 2 diabetes, casein elicits a slower and more gradual insulin and incretin response compared to whey, leading to moderated postprandial glycemia." (PMID 41305580, 2025). "Insulin resistance, defined by impaired insulin signaling which results in diminished glucose uptake and dysregulated energy metabolism, is frequently preceded the onset of glucose intolerance and type 2 diabetes mellitus (T2DM)." (PMID 40959572, 2025). "Chronic diabetes conditions include type 1 diabetes (T1D) and type 2 diabetes (T2D), which are both characterized by hyperglycemia, or high levels of glucose in the blood, due to insufficient and/or inefficient insulin production." (PMID 40564574, 2025). "Four had type 1 and six had type 2 diabetes and all used insulin pens and self‐managed their insulin treatment before admission." (PMID 41358572, 2025). "In the context of beta cell dysfunction and type 2 diabetes progression, a critical subset of proteins involved in insulin secretion is subject to regulation through ubiquitination-mediated degradation." (PMID 41373704, 2025). "The SURPASS-5 (Study of Tirzepatide in Participants With Type 2 Diabetes on Insulin Glargine) trial demonstrated that switching to tirzepatide from insulin therapy significantly reduced insulin requirements." (PMID 40746803, 2025). "Type 2 diabetes (T2D) is a complex genetic disorder due to the alteration of insulin secretion from pancreatic beta cells." (PMID 40869173, 2025). "Type 2 diabetes (T2D) predominantly involves dysfunction of β cells that have been challenged to sustain a high level of compensatory insulin secretion due to insulin resistance." (PMID 40762838, 2025). "Offspring conceived with ART show a higher incidence of resistance to insulin and Type 2 diabetes in adulthood." (PMID 41323197, 2025). "Biphasic insulin secretion, which fails in type 2 diabetes, can be provoked by various nutrient stimuli, glucose being the superior physiological one." (PMID 40154614, 2025). "In study I, we compared plasma BCAA levels measured before and after 2 h of insulin in individuals with type 2 diabetes, glucose-tolerant individuals with obesity and lean individuals." (PMID 40404819, 2025). "In clinical practice, people with type 3c diabetes are most commonly classified as having type 2 diabetes but have worse glycaemic control and a greater requirement for insulin." (PMID 39762966, 2025). "While insulin therapy is vital for managing both Type 1 and Type 2 diabetes, traditional methods such as subcutaneous injections have notable drawbacks, including pain, discomfort, and difficulty in maintaining stable blood sugar levels." (PMID 40352348, 2025). "Bisphenol A and phthalates disrupt m6A levels in pancreatic β-cells, impairing insulin secretion and promoting type 2 diabetes." (PMID 40760453, 2025). "Type II diabetes mellitus (T2DM) is characterized by elevated blood glucose due to impaired insulin secretion/sensitivity." (PMID 39991230, 2025). "The insulin secretion data from the NGT and type 2 diabetes groups have been published previously, showing a lower insulin secretion rate (ISR) after both the oral (p=0.001) and intravenous (p=0.002) stimulus in the BA type 2 diabetes group." (PMID 40768046, 2025). "Based on these findings, the patient was diagnosed with type 2 diabetes and treated with intensive insulin therapy." (PMID 40310300, 2025).
type 2 diabetes (continued). "The effects of olive oil on type 2 diabetes (T2DM) risk and insulin sensitivity are deeply influenced by the broader dietary context in which it is consumed." (PMID 39940428, 2025). "Over 95% of diabetic patients have type 2 diabetes, which is characterized by dysfunction in insulin secretion from pancreatic β-cells and insulin resistance." (PMID 41153992, 2025). "Tailored exercise interventions and physical activity are cornerstones in managing type 2 diabetes mellitus (T2DM), providing benefits such as improved insulin sensitivity and reduced cardiovascular disease risk." (PMID 40278718, 2025). "After childbirth, participants experienced anxiety related to potential long-term risks of impaired insulin function or developing type 2 diabetes." (PMID 41257627, 2025). "Previously, we encountered a patient (in this case, with type 2 diabetes) who, despite decreased insulin secretion necessitating insulin therapy, was prescribed an SGLT2 inhibitor." (PMID 41373820, 2025). "Type 2 diabetes develops mainly because of impaired insulin action, insufficient insulin secretion, or a combination of both." (PMID 41517158, 2025). "This dual impact on both insulin sensitivity and insulin secretion promotes a pathological loop that accelerates metabolic deterioration and contributes to the progression of type 2 diabetes." (PMID 40870478, 2025). "In diabetic individuals, especially those with type 2 diabetes, vitamin E consumption dramatically lowers fasting insulin, HOMA-IR, and HbA1c values." (PMID 39940428, 2025). "The first published trial, QWINT-2 (NCT05362058), compared once-weekly efsitora to daily degludec in 928 insulin-naive adults with type 2 diabetes." (PMID 40937414, 2025). "Despite the critical role of β-cell function and insulin sensitivity in the pathophysiology of type 2 diabetes, studies that have accurately evaluated β-cell function and insulin sensitivity during menopause remain limited." (PMID 40361840, 2025). "A prior study demonstrated an improved vascular response (vascular stiffness and microvascular perfusion) to insulin in cardiac and skeletal muscles in 11 subjects with type II diabetes after treatment with empagliflozin." (PMID 40281528, 2025). "In summary, Z. officinale powder has shown positive effects on weight management, insulin sensitivity, and lipid profiles in various health conditions, including obesity, type-2 diabetes, and NAFLD." (PMID 40343290, 2025). "A total of 960 participants (96%) had type 2 diabetes, with 468 of 997 (47%) requiring insulin, 153 (15%) taking sodium-glucose cotransporter 2 inhibitors, and 102 (10%) taking L agonists at baseline." (PMID 40029647, 2025). "Through its enzymatic function, DPP4 regulates insulin secretion and serves as a key therapeutic target in type 2 diabetes mellitus, where its inhibition enhances GLP−1 activity to promote glycemic control." (PMID 41334589, 2025). "These interactions correlate with in vivo findings showing that tannin- and gallic acid-rich extracts improve glucose homeostasis and insulin sensitivity in type 2 diabetes models." (PMID 40463898, 2025). "In metabolic disorders, it helps regulate insulin sensitivity, glucose metabolism, and lipid accumulation—thereby improving conditions such as type 2 diabetes and obesity." (PMID 40709093, 2025). "In type 2 diabetes (T2D), insulin secretion is impaired, marked by a reduced first-phase response and disrupted oscillatory patterns, typically with higher frequency and lower amplitude pulses." (PMID 41356346, 2025). "Oral antidiabetic medication is the primary therapy for type 2 diabetes (T2D), although insulin can also be administered to people with severe insulin‐dependent T2D." (PMID 41019174, 2025). "This work reveals a previously unrecognized macrophage–β-cell communication axis with therapeutic potential for restoring insulin secretion in metabolic diseases such as obesity and type 2 diabetes." (PMID 41278909, 2025).
type 2 diabetes (continued). "Increased muscle mass and strength correlate with both improved insulin sensitivity and upregulation of GLUT-4 transporters, reducing the risk of type 2 diabetes." (PMID 40430117, 2025). "A key factor in managing type 2 diabetes with insulin is maintaining a balance between achieving good glycaemic control and minimising the risk of hypoglycaemia." (PMID 39820580, 2025). "Wnt/β-catenin signaling is involved in insulin secretion, β-cell proliferation, and glucose metabolism, and dysregulation of this pathway contributes to the development of type 2 diabetes and its complications." (PMID 41155632, 2025). "In contrast, TRE reduced insulin levels, in women with polycystic ovarian syndrome, in subjects with type 2 diabetes, in men with prediabetes and in healthy individuals." (PMID 39899119, 2025). "During physical activity, increased glucose requirements and insulin sensitivity can lead to hypoglycaemia in individuals with type 2 diabetes on insulin therapy." (PMID 40186685, 2025). "For each w8 ​ value, an input-output dataset of 1,000 samples is generated during the modeling phase to identify type 2 diabetes in the insulin-glucose regulatory system using FRNN." (PMID 41345203, 2025). "Findings show that intermittent fasting has the potential to become a promising therapy option in people with insulin-treated type 2 diabetes." (PMID 40705196, 2025). "Supplementation of C. verum in obese individuals with type-2 diabetes resulted in enhanced ghrelin secretion, decreased BMI and waist circumference, and lowered levels of blood glucose and insulin." (PMID 40343290, 2025). "The proportion of patients treated with insulin was higher in the hospital-based multidisciplinary group, both considering the totality patients and those affected by type 2 diabetes (71.6% vs. 32.2%; p < 0.001, and 58.8% vs. 31.0%; p = 0.004 respectively)." (PMID 39160371, 2025). "Exercise plays a crucial role in maintaining metabolic health, enhancing muscle function, and improving insulin sensitivity, thereby preventing metabolic diseases such as type 2 diabetes." (PMID 40004204, 2025). "Abstract figure legend The figure illustrates the impact of high‐intensity interval training (HIIT) on skeletal muscle metabolism and insulin sensitivity in individuals with type 2 diabetes and healthy controls." (PMID 40413649, 2025). "Resistin, mainly secreted from macrophages in humans, is described as a hormone linking obesity to type 2 diabetes mellitus, a disorder marked by dysregulated glycemia due to impaired insulin dynamics and glucagon excess." (PMID 40699839, 2025). "After applying all inclusion and exclusion criteria, 52,394 people with type 2 diabetes using non‐insulin therapies were identified." (PMID 40851538, 2025). "In comparison, a study using bulk RNA‐sequencing of muscle samples from severely insulin‐resistant, insulin‐treated individuals with type 2 diabetes and healthy controls reported 117 DEGs." (PMID 40413649, 2025). "The characteristics of Type 1 diabetes (T1DM) are the destruction of pancreatic β cells and insulin deficiency, while Type 2 diabetes (T2DM) is primarily caused by insulin resistance (IR) and insufficient insulin secretion." (PMID 40072093, 2025). "For instance, RL is used to personalize insulin dosing for patients with type 1 and type 2 diabetes, as well as dietary decisions." (PMID 40406780, 2025). "These agents offer a unique, insulin-independent mechanism of action, making them valuable in managing type 2 diabetes and CKD." (PMID 40872522, 2025). "Individuals with the concentration of serum ferritin in Type II diabetes mellitus can affect insulin sensitivity, oxidative damage, viscosity, and vascular resistance." (PMID 39817379, 2025). "Pancreatic islet β-cells are the sole source of endogenous insulin, and our understanding of β-cell dysfunction and death in type 2 diabetes (T2D) is incomplete." (PMID 40982369, 2025).
type 2 diabetes (continued). "One study in patients with type 2 diabetes and periodontitis found that after periodontal scaling, patients showed improved insulin sensitivity and better glucose control, reflected in decreased fasting blood glucose levels and improved HbA1c." (PMID 40136728, 2025). "In type II diabetes, increased levels of PA induce the loss of the β-cell function due to the involvement of FFAR1 in crosstalk with mTOR-Akt and IRS-1, altering insulin signaling." (PMID 39859502, 2025). "Type 2 diabetes mellitus (T2DM) is a chronic metabolic disorder characterized by insulin resistance and progressive pancreaticβ-cell dysfunction, leading to hyperglycemia and associated complications." (PMID 41393459, 2025). "SCFAs have been demonstrated to have a beneficial effect on insulin sensitivity, which is pivotal in the regulation of blood glucose levels and the prevention of type 2 diabetes." (PMID 40650200, 2025). "In the present analysis, we investigate the burden of hypoglycemia and hyperglycemia during FCL insulin delivery in adults by type of diabetes (type 1 and type 2 diabetes) over the 24-hour period." (PMID 38613227, 2025). "Periodic evaluation of endogenous insulin secretion is necessary, and basic pharmacotherapy should be performed in accordance with the treatment guidelines for type 2 diabetes, except for the use of sulfonylurea agents." (PMID 40226121, 2025). "Some patients with type 2 diabetes have excessive insulin secretion, which leads to a certain extent to affect the efficacy after insulin use, so drug treatment is usually used." (PMID 40362847, 2025). "Repaglinide is an oral insulin secretagogue of the meglitinide class, used primarily for the management of postprandial hyperglycemia in patients with type 2 diabetes mellitus." (PMID 41011221, 2025). "Complementary therapies like probiotic supplements are gaining popularity, but traditional treatments like medication, insulin therapy, and lifestyle changes continue to be the mainstay of managing type 2 diabetes." (PMID 40003720, 2025). "In a study conducted on rats with type 2 diabetes, it was demonstrated that obestatin administered over a period of 30 days had a modulatory effect on blood insulin and glucose concentrations." (PMID 40806524, 2025). "Another limitation of the study is the inability to differentiate between patients with type 1 and type 2 diabetes who use insulin." (PMID 41171710, 2025). "Key findings show that HIIT improved insulin sensitivity in both groups, but individuals with type 2 diabetes exhibited a blunted myonuclear metabolic transcriptional response." (PMID 40413649, 2025). "Chronic treatment improved mitochondrial morphology, increased insulin granule content, and reduced β-cell apoptosis, highlighting Imeglimin’s direct role in preserving β-cell function in type 2 diabetes." (PMID 40822946, 2025). "Beta cells play a central role in glucose homeostasis by secreting insulin in response to rising blood glucose, thus their function has been a therapeutic target for both obesity and type 2 diabetes." (PMID 40099262, 2025). "Therapeutically, OX1R-selective agonists hold promise for β-cell rescue and hypoglycemia countermeasures, while timed DORAs, such as suvorexant, offer a novel approach to nocturnal hepatic insulin resistance in type 2 diabetes." (PMID 41438219, 2025). "This is supported by the observation that K+ channel openers reduce insulin secretion, ultimately improving insulin production in individuals with type 2 diabetes by reducing the workload of beta cells." (PMID 39496966, 2025). "Type 1 diabetes differs from type 2 diabetes because autoimmunity in type 2 diabetes results in beta-cell decline, which increases insulin dependency progressively over time." (PMID 40225541, 2025).